CTLA4 (cytotoxic T-lymphocyte associated protein 4)
Diseases named in the same sentence as CTLA4 in open-access papers (continued):
Sharing a sentence is not in itself a finding about the gene and the disease.
cancer (continued). "These include immune checkpoints such as PD-L1 and CTLA-4, which enable cancer cells to evade the immune system by putting “brakes” on immune responses." (PMID 40004038, 2025). "For instance, dual checkpoint blockade, such as the combination of anti-PD-1 and anti-CTLA-4 antibodies, has shown improved outcomes in several cancer types." (PMID 40361336, 2025). "ICB extends beyond targeting PD-1 and CTLA-4, with novel therapies and engineered approaches in cancer also holding promise for HIV treatment." (PMID 40682400, 2025). "Although our focus has been on CTLA4 expressed in cancer cell lines, we have also shown that our findings with respect to USP8 and CTLA4 translate to T cells." (PMID 39404738, 2025). "CTLA-4 inhibitors work by blocking the CTLA-4 which enhances the immune response to fight the cancer cells." (PMID 40547025, 2025). "Their mechanism of action involves inhibiting cytotoxic T lymphocyte-associated antigen 4 (CTLA4) and programmed cell death 1 (PD-1) on T-cells, or its ligand (PDL-1), leading to enhanced T-cell activation and immune activity against cancer cells." (PMID 40823470, 2025). "While cancer therapies like PD-L1 and CTLA-4 inhibitors have advanced immunotherapy, their effectiveness remains limited." (PMID 39898257, 2025). "Despite the transformative advances brought by anti-PD-1/L1 and anti-CTLA-4 therapies, achieving a universal breakthrough in cancer immunotherapy remains challenging." (PMID 39857682, 2025). "ICIs are monoclonal antibodies against key regulatory proteins such as programmed death 1 and its ligand (PD1-PDL1) or cytotoxic T-lymphocyte-associated protein 4 (CTLA4), enhancing the immune response against cancer cells." (PMID 41158469, 2025). "GBM and KIRC are a few examples; also, PD-1 inhibitors (Nivolumab, Pembrolizumab, and Cemiplimab), PDL-1 inhibitors (Atezolizumab, Durvalumab, and Avelumab), CTLA-4 inhibitors (Ipilimumab) are approved by the USFDA for the treatment of cancers." (PMID 40277760, 2025). "Immune checkpoint inhibitors, such as PD-1/PD-L1 and CTLA-4 inhibitors, boost the immune system’s ability to target and eliminate cancer cells." (PMID 40563308, 2025). "From an oncological perspective, one key feature of CTLA-4 is its role in facilitating the immune evasion by cancer cells, as these cells utilize mechanisms that result in the overexpression of CTLA-4, thereby suppressing the immune response against them." (PMID 41141615, 2025). "(i) Ipilimumab: Ipilimumab is an only anti-CTLA-4 monoclonal antibody (fully human IgG1) approved by the US FDA for cancer treatment." (PMID 40922740, 2025). "Immune checkpoint inhibitors, such as anti-PD-1 and anti-CTLA-4 antibodies, have shown remarkable efficacy in enhancing antitumor immune responses and improving patient outcomes in cancer." (PMID 40563999, 2025). "Some ICIs have been approved as cancer immunotherapy, as they target CTLA4/CD80, or PD-1/PD-L1 interaction." (PMID 41339932, 2025). "For example, a classical immunotherapy combination involving a PD-1 inhibitor and a CTLA-4 inhibitor has been approved for the treatment of various cancers." (PMID 40739089, 2025). "However, chronic antigen exposure, as seen in persistent viral infections and cancer, can drive T cells towards a state of functional exhaustion, characterized by progressive loss of effector function and sustained expression of inhibitory receptors like PD-1 and CTLA-4." (PMID 41262872, 2025). "Pharmacological inhibition of FAO using etomoxir, a CPT1A inhibitor, has been shown to restore T-cell effector function and synergize with CTLA-4 blockade in preclinical cancer models." (PMID 41562065, 2025). "With less than 5% of the human proteome being considered short-lived (t1/2 < 8 h), CTLA-4 stands out as a remarkably unstable membrane receptor across cancer cells and T cells." (PMID 41031910, 2025). "Preclinical studies have reported augmented anti-cancer immune effects when CTLA-4 inhibitors are combined with HSP90 inhibitors." (PMID 40872476, 2025).
cancer (continued). "Intriguingly, a small sample of PLWH who received cICB treatment (targeting PD-1 and CTLA-4) for comorbid cancers saw a marked increase in CD8+ T cell effector function and significant decreases in replication competent HIV-1, respectively." (PMID 40875618, 2025). "A deeper understanding of checkpoint inhibitors like PD-1/PD-L1 and CTLA-4 has paved the way for advancements in monoclonal antibodies (mAbs) targeting these proteins, improving cancer therapy." (PMID 40075727, 2025). "The immunoglobulin-associated receptor family (TIGIT, CTLA4, CD274, and BTLA) have inhibitory effects on T cell function and have been used as a part of immunomodulatory strategy for treating cancers." (PMID 40173324, 2025). "Here, we first show that CTLA4 is endogenously expressed as a short-lived protein in selected cancer cell lines, where it is degraded in lysosomes." (PMID 39404738, 2025). "ICI involves the use of antibodies to block receptors such as PD-1 and CTLA-4; receptors utilised by cancer cells to dampen the immune response by inhibiting the activation of T-cells creating an immunosuppressant environment." (PMID 40092697, 2025). "Single-cell RNA-seq analysis revealed an altered Treg compartment in cancer patients after anti–CTLA-4 and anti–PD-1 treatment." (PMID 41026527, 2025). "CTLA-4 ICI Ipilimumab (Yervoy) has been approved by the FDA for multiple cancers, including melanoma, renal cell carcinoma, and non-small cell lung cancer." (PMID 40227644, 2025). "Approximately two-third of patients were treated with PD-1 inhibitors, particularly pembrolizumab and nivolumab, whereas PD-L1 inhibitors and CTLA-4 inhibitors were administered in 19.1% and 4.8% of cancer patients." (PMID 40547024, 2025). "In 2018, the Nobel Prize was awarded to recognize the groundbreaking work on CTLA-4 and PD-1 pathways that established the field of cancer immunotherapy." (PMID 39995677, 2025). "Since the first FDA approval of anti-CTLA-4 (Ipilimumab) in 2011, cancer immunotherapies are rapidly evolving, over half a dozen ICI therapies are already approved, and combinations are being extensively evaluated." (PMID 40313772, 2025). "CDH13 expression is linked to immune cell infiltration, affects cancer prognosis and can be downregulated by anti-PD1/CTLA-4/PD-L1 immunotherapy." (PMID 41164751, 2025). "The treatment of cancer patients with immune checkpoint inhibitors (such as anti-CTLA-4, anti-PD-1, anti-PD-L1, or combinations of anti-PD-1/PD-L1 with anti-CTLA-4) has marked a major breakthrough in oncology in recent years." (PMID 39325360, 2025). "Abnormal circadian rhythms have been linked to upregulation of immune inhibitory molecules such as PD-L1 and CTLA-4, contributing to T cell exhaustion and immune evasion in cancer." (PMID 40191195, 2025). "Immunosuppressive checkpoints, such as PD‐L1 and CTLA‐4, can help cancer cells evade immune surveillance via different mechanisms." (PMID 39912421, 2025). "While immune checkpoint inhibitors (ICIs), such as anti-PD-1/PD-L1 and anti-CTLA-4 antibodies, have revolutionized cancer treatment in adults, their application in pediatric sarcomas has shown limited success." (PMID 41007114, 2025). "The introduction of immune checkpoint inhibitors (ICIs) has transformed cancer treatment, with monoclonal antibodies targeting CTLA-4, PD-1, and PD-L1 demonstrating clinical success." (PMID 40536609, 2025). "The development of ICI, such as CTLA-4 and PD-1/PD-L1 inhibitors, has transformed cancer therapy by demonstrating remarkable antitumor efficacy." (PMID 40361336, 2025). "The discovery of the PD-1 receptor and its ligand PD-L1 revolutionized our understanding of immune regulation and, together with that of CTLA-4, allowed the development of immune checkpoint blockade, now a cornerstone of cancer therapy." (PMID 41425548, 2025).
cancer (continued). "Although most patients do not respond to these immunotherapies, therapeutic antibodies against PD‐1, PD‐L1 or CTLA4 have markedly increased progression‐free survival and overall survival in various cancers, especially when combined with chemotherapy." (PMID 38775116, 2025). "Immunotherapy of cancer through inhibition of the immune checkpoints CTLA-4 and PD-1/PD-L1 has led to dramatic improvements in survival for patients who respond to these treatments across several cancer types." (PMID 40428397, 2025). "Compared with alternative ICIs,anti-PD-L1 monoclonal antibodies, including anti-CTLA-4 monoclonal antibodies, have shown prolonged beneficial effects in a diverse array of human cancer patients and exhibit reduced toxicity." (PMID 40064803, 2025). "Anti-CTLA-4 therapy enhances the antigen-specific T cell-dependent immune response, while anti-PD-1/PD-L1 activates the ability of cytotoxic T cells to lyse cancer cells, resulting in mutually synergistic effects when delivered together." (PMID 39941829, 2025). "Immune checkpoint inhibitors (ICIs) targeting PD-1, PD-L1, and CTLA-4 have shown significant therapeutic potential in various cancers." (PMID 40535771, 2025). "Through clinical trials and efficacy evaluations, ipilimumab, a CTLA-4 monoclonal antibody, has become the first ICIs approved for cancer treatment, which stimulates effective immune responses while suppressing tumor progression." (PMID 39228005, 2024). "Cytotoxic T-lymphocyte-associated protein 4 (CTLA-4), also known as CD152, is another important immune checkpoint protein involved in the suppression of immune defenses against cancer, encoded by the CTLA-4 gene." (PMID 38893211, 2024). "Proof of the significance of a well-functioning anti-cancer immune system is the demonstrated efficacy of immunotherapy, with anti-PD-1 and anti-CTLA-4 antibodies standing out as notable examples." (PMID 39474426, 2024). "Novel immune treatments for oncology, such as mAbs, aiming at CTLA-4 and the PD-1/PD-L1 axis, exemplify the advances in innovative cancer immunotherapies and have revolutionized the landscape of cancer therapy." (PMID 39339252, 2024). "Currently, anti-CTLA-4 agents such as Ipilimumab and Tremelimumab are broadly applied as therapeutic agents in clinical studies of different cancers." (PMID 39687617, 2024). "Antibodies that obstruct immune checkpoints, namely Cytotoxic T-Lymphocyte Associated Protein 4 (CTLA-4) and PD-1/PD-L1, have proven highly successful in cancer immunotherapy." (PMID 39220871, 2024). "By blocking the checkpoint molecules such as CTLA-4, PD-1, and PD-L1 from binding with their partner proteins, ICIs inhibit the ‘off’ signal, activating T cells and promoting the killing of cancer cells." (PMID 39135760, 2024). "These drugs are based on anti-CTLA-4 antibodies, and it is necessary to adopt approaches that use similar molecular mechanisms and nanobody-based anti-CTLA-4 drugs to treat diseases, especially types of cancers." (PMID 38191571, 2024). "Immunotherapy using antibodies that target the checkpoint proteins CTLA-4, PD-1, and PD-L1 is improving the treatment of some cancers; however, combination therapies that will provide broader and more sustained clinical responses are desired." (PMID 38730731, 2024). "Manipulation of this pathway has been a focus of several immunomodulatory therapies including in cancer, where CTLA-4 blockade has been shown to limit tumor growth in various murine models and in several human cancers." (PMID 38226924, 2024). "Blocking PD-1, PD-L1, or CTLA-4 can reinvigorate T cells, allowing them to recognize and effectively attack cancer cells." (PMID 39329702, 2024). "Despite promising results in certain cancers, there are several challenges surrounding CTLA-4 blockade therapy." (PMID 39346924, 2024).
cancer (continued). "These antibodies target molecules like cytotoxic T-lymphocyte antigen 4 (CTLA-4), programmed death receptor 1 (PD-1), and programmed death ligand 1 (PD-L1), ushering in a new era in the treatment of various types of cancers." (PMID 38672581, 2024). "The use of immune checkpoint inhibitors (ICIs), including antibodies that specifically target PD-L1, PD-1, and CTLA-4, has resulted in a substantial revolution in the field of cancer immunotherapy." (PMID 38451188, 2024). "Antibodies blocking CTLA-4 or PD-1 have shown antitumor activity in preclinical and clinical settings, and combination therapy has demonstrated improved responses in various cancers." (PMID 38475778, 2024). "The research delves into how the composition of the gut microbiota influences the therapeutic efficacy of immune checkpoint inhibitors, specifically CTLA-4 inhibition, in individuals with advanced cancer." (PMID 39351241, 2024). "The combined blockade of CTLA-4 and PD-1 is supported by a robust immunological rationale and has been established as a standard option in certain cancers like kidney cancer or melanoma." (PMID 39335671, 2024). "Although most immunotherapy studies have focused on PD-L1 and CTLA4, many studies have shown that other immune checkpoints potential play an essential role in suppressing the immune response and allowing cancer progression." (PMID 38418707, 2024). "Impressive results in a subset of cancers have been obtained using immunotherapies such as checkpoint inhibitors (i.e. anti-CTLA4, anti-PD-1, and anti-PD-L1) and CAR T therapies." (PMID 38449858, 2024). "In order to develop a novel approach for cancer treatment, it is crucial to incorporate HLA-G antibodies together with antibodies that target immune checkpoints, such as PD-1, CTLA-4 and TIM-3." (PMID 38391781, 2024). "Checkpoint inhibitors work by targeting proteins such as PD-1/PD-L1 and CTLA-4, which are utilized by cancer cells to avoid detection by the immune system." (PMID 39272660, 2024). "Checkpoint inhibitors, including CTLA-4 and PD-1/PD-L1 inhibitors, have demonstrated significant clinical efficacy in various cancer types." (PMID 38198170, 2024). "Immune checkpoint blockade (ICB) therapies that target cytotoxic T lymphocyte antigen 4 (CTLA-4), programmed cell death protein 1 (PD-1) or programmed cell death ligand 1 (PD-L1) have resulted in durable antitumor responses in a subset of cancer patients." (PMID 39343508, 2024). "Programmed cell death protein 1 (PD-1)/PD-L1 and cytotoxic T lymphocyte-associated antigen 4 (CTLA-4) are inhibitory checkpoint receptors that suppress T cell activation, affecting the immune response against cancer." (PMID 39767682, 2024). "Epithelial cancer cells, through the PD-1/PD-L1 pathway, and mesenchymal cancer cells, through the CTLA-4/CD80 and TIGIT/CD155 pathways, differentially block antitumor immune responses and determine the response to ICB therapies." (PMID 38914547, 2024). "ICIs use specific monoclonal antibodies (mabs), including anti-programmed death-1 (PD-1)/programmed death-ligand 1 (PD-L1) and/or anti-cytotoxic T-lymphocyte antigen-4 (CTLA-4), to treat several cancers." (PMID 38612436, 2024). "Overexpression of CTLA-4 can competitively inhibit the CD28 co-stimulatory signal required for optimal T cell activation, leading to a loss of anti-cancer activity." (PMID 39995821, 2024). "Antibody blockade of PD-1 or its ligand PD-L1 appears to be even more effective than anti-CTLA-4 in enhancing T cell tumor killing and preventing the progression of cancer in patients." (PMID 39204136, 2024). "This is a new paradigm in cancer research, wherein altering the pH sensitivity and recyclability of anti-CTLA-4 mAbs through lysosomal characteristics can simultaneously enhance its safety and efficacy." (PMID 38370407, 2024). "The clinical significance of CTLA-4 and PD-1 expression in targeted cancer treatment has been acknowledged due to their ability to inhibit T cell proliferation." (PMID 38476263, 2024).
cancer (continued). "Immune‐checkpoint inhibitors (ICIs), involving anti‐CTLA‐4 and anti‐PD‐1 antibodies, have emerged as effective cancer treatments over the past decade." (PMID 38881673, 2024). "Over the past decade, antibodies that target immune inhibitory receptors such as cytotoxic T lymphocyte-associated antigen 4 (CTLA-4), programmed Death 1 (PD-1), and its ligand (PD-L1) have been extensively utilized in the field of cancer treatment." (PMID 38462628, 2024). "Checkpoint inhibitors targeting PD-L1, PD1, and CTLA4 have been shown to enhance the immune response in solid tumors and revolutionize cancer immunotherapy." (PMID 39594778, 2024). "These inhibitors target CTLA-4, a key regulator of T cell activation, and have shown promise in enhancing the immune response against cancer cells." (PMID 39275127, 2024). "Immunotherapies, such as CTLA-4 and PD-1/PD-L1 inhibitors, represent innovative and promising approaches to cancer treatment." (PMID 38720389, 2024). "The emergence of ICIs, mainly including PD-1/PD-L1, LAG-3, and CTLA-4 monoclonal antibodies (mAbs), has shaped the therapeutic landscape of some types of cancers." (PMID 39687617, 2024). "The three phase I/II clinical trials use EGFR CAR-T cells expressing antibodies anti-PD-L1/CTLA-4, underscoring the utility of checkpoint inhibition in cancer immunotherapy (NCT03182816, NCT02873390, NCT02862028)." (PMID 38727261, 2024). "Ipilimumab was approved by the FDA in 2011 as the first example of mAbs used in cancer therapy targeting an immune checkpoint (CTLA-4) and represents a revolution in cancer treatment." (PMID 38543102, 2024). "By blocking CTLA-4, ICIs enhance T cell activation and proliferation, improving immune system function against cancer cells." (PMID 39347217, 2024). "As a therapeutic antibody, ipilimumab works against CTLA-4 in an effort to boost antitumor immunity and interfere with the complex mechanisms that cancer cells use to survive." (PMID 38931856, 2024). "Our findings support the use of small molecules as alternatives to antibodies targeting CTLA-4 in cancer therapy." (PMID 38312352, 2024). "Ipilimumab inhibits CTLA-4, preventing its inhibitory signal and allowing immune cells to remain active and attack cancer cells." (PMID 38201308, 2024). "For instance, immune checkpoint inhibitors include antibodies targeting PD-1, PD-L1), and cytotoxic T-lymphocyte-associated protein 4 (CTLA-4) loaded in EVs and can stimulate an immune response, leading to the targeted elimination of cancer cells." (PMID 39219215, 2024). "This has been reported as part of targeting CTLA-4 and with novel anti-cancer therapies targeting novel checkpoints." (PMID 38533720, 2024). "Currently, the dual immunotherapy that combines PD-1/PD-L1 and CTLA-4 inhibitors has received approval for various cancer indications, such as the nivolumab + ipilimumab regimen, a combination of PD-1 and CTLA-4 inhibitors." (PMID 39068460, 2024). "ICIs, such as those targeting PD-1/PD-L1 and CTLA-4, have revolutionized cancer therapy by enhancing the immune system’s ability to recognize and destroy cancer cells." (PMID 39001498, 2024). "In summary, we observed a statistically significant association between co-occurring infections and immune-related adverse events in cancer patients treated with PD-1, PD-L1, or CTLA-4 inhibitors." (PMID 39199593, 2024). "Immunotherapy with checkpoint-blocking antibodies targeting CTLA-4 and PD-1/PD-L1 has revolutionized cancer treatment and drastically improved the survival of individuals in the clinical treatment." (PMID 38168435, 2024). "The blockade of CTLA-4, along with the PD-1/PD-L1 axes, constitutes the foundation of current cancer immunotherapy." (PMID 38473398, 2024). "Immune checkpoint inhibitors such as PD-1/PDL-1 and CTLA-4 blockers have brought about a paradigm shift in the management of advanced cancers." (PMID 38731962, 2024).